IL20RA (interleukin 20 receptor subunit alpha)
Description:
The IL20RA/IL20RB dimer is a receptor for IL19, IL20 and IL24. The IL20RA/IL10RB dimer is a receptor for IL26.
Synonyms: IL-20R-alpha; IL-20RA; CRF2-8; ZCYTOR7; IL-20R1
Tractability: Antibody: its Gene Ontology location is reachable by antibodies, with high confidence; UniProt predicts a signal peptide or a membrane-spanning region.
Gene: Protein-coding gene on chromosome 6 (136,999,971 to 137,045,180, reverse strand). Ensembl gene ENSG00000016402.
Subcellular location: Membrane
Subcellular location (Human Protein Atlas): Cytosol
Pathways (Reactome):
Immune System: Interleukin-20 family signaling
Gene Ontology:
Molecular function: protein binding; coreceptor activity; cytokine receptor activity; interleukin-20 binding
Biological process: interleukin-19-mediated signaling pathway; apoptotic process; cell surface receptor signaling pathway via JAK-STAT; cellular response to interleukin-4; cytokine-mediated signaling pathway; dendritic cell differentiation; inflammatory response; negative regulation of type II interferon production; osteoclast differentiation; positive regulation of interleukin-13 production; positive regulation of interleukin-4 production; regulation of cell population proliferation
Cellular component: interleukin-20 receptor complex; plasma membrane; receptor complex; membrane
Genetic constraint (gnomAD): Loss-of-function variants: 26 observed, 32.93 expected, observed/expected ratio (o/e) 0.79, 90% interval 0.58 to 1.1. The upper end of that interval is the gene's LOEUF score, 1.1, which puts it in group 4 of 6, group 1 being the genes least tolerant of losing a copy. Missense variants: 634 observed, 658.42 expected, observed/expected ratio (o/e) 0.96, 90% interval 0.9 to 1.03. Synonymous variants: 271 observed, 263.74 expected, observed/expected ratio (o/e) 1.03, 90% interval 0.93 to 1.14.
Homologues: Orthologues: chimpanzee IL20RA (99% identical), macaque IL20RA (96% identical), pig IL20RA (74% identical), dog IL20RA (73% identical), rabbit IL20RA (72% identical), mouse Il20ra (64% identical), rat Il20ra (61% identical), guinea pig IL20RA (59% identical), zebrafish il20ra (23% identical). Paralogues in human: IL22RA1 (17% identical), IL10RA (15% identical), IFNLR1 (14% identical), IL22RA2 (14% identical), IFNGR1 (13% identical), IFNAR2 (13% identical), IFNAR1 (13% identical), IL10RB (12% identical), F3 (10% identical), IL20RB (10% identical), IFNGR2 (10% identical).
Diseases named in the same sentence as IL20RA in open-access papers:
IL20RA is named in the same sentence as 67 diseases in open-access papers, as found by Europe PMC text mining. Sharing a sentence is not in itself a finding about the gene and the disease. The quoted sentences say what the papers report.
breast cancer (9 papers, 2021 to 2025). A primary or metastatic malignant neoplasm involving the breast. "IL20RA, showing a higher association with IL-19 revealed a significant outcome on the OS of breast cancer patients." (PMID 37675062, 2023). "Interleukin 20 receptor subunit alpha (IL20RA) increases the ratio of SP to ALDHbr in breast cancer cells, improves sphere-forming capacity, stimulates the production of key stem cell genes such as Sox2 and Oct4, and boosts chemoresistance." (PMID 40097979, 2025). "Studies demonstrated that IL-20RA promotes stemness features and increases the tumor-initiating ability of breast cancer cells via the JAK1-STAT3-SOX2 signaling pathway." (PMID 36859240, 2023). "The expression of IL20RA was also detectable in four mouse breast cancer cell lines: 4TO7, EO771, 4T1, and EMT6." (PMID 33456560, 2021). "Latest research showed that IL-20RA regulated the stemness of breast cancer cells and provided immune microenvironment for the development of breast cancer." (PMID 34336707, 2021). "The relatively higher expression of IL20RA was also found in the human breast cancer cell lines, including MDA-MB-231, MDA-MB-453, T-47D, MCF-7, and ZR-75-1, compared with the non-tumorigenic breast epithelial cell line MCF 10A." (PMID 33456560, 2021). "We found that IL20RA signaling promoted various stemness properties of breast cancer cells, including higher ALDH activity, increased sphere formation ability, and increased proportion of SP cells, and enhanced resistance to chemotherapeutic agents in vitro." (PMID 33456560, 2021). "We found that IL20RA promotes stemness features and increases the tumor-initiating ability of breast cancer cells via the JAK1-STAT3-SOX2 signaling pathway." (PMID 33456560, 2021). "IL-20RA expression was significantly increased in prostate cancer, breast cancer and non-small cell lung cancer." (PMID 34336707, 2021). "As IL20RB is a functional partner of IL20RA, its effects on the stemness properties of breast cancer cells were also investigated." (PMID 33456560, 2021). "Enzyme-linked immunosorbent assay and TCGA dataset analysis were performed to determine the function of IL20RA signaling in breast cancer progression." (PMID 33456560, 2021). "IL20RA also promoted the tumor-initiating capacity of breast cancer cells and tumor growth in vivo." (PMID 33456560, 2021). "In this study, the roles of IL20RA in breast cancer progression and stemness were investigated." (PMID 33456560, 2021). "Moreover, IL20RA promotes the chemoresistance of breast cancer cells and upregulates the expression of PD-L1 to compromise the activity of anti-cancer immune cells." (PMID 33456560, 2021). "IL20RA promotes the tumor-initiating ability and lung metastasis of breast cancer cells in vivo." (PMID 33456560, 2021). "Another study found that IL20RA expression was elevated in breast cancer and colorectal cancer." (PMID 34868990, 2021). "IL20RA increases the SP and ALDHbr proportions of breast cancer cells, enhances the sphere formation ability, and promotes the expression of core stemness genes, such as Sox2 and Oct4, as well as increases chemoresistance of breast cancer cells." (PMID 33456560, 2021). "In conclusion, we found that IL20RA could regulate the stemness of breast cancer cells and promote a cancer-favorable immune microenvironment." (PMID 33456560, 2021). "In this study, we found that IL20RA expression was elevated in breast cancer and colorectal cancer." (PMID 33456560, 2021). "Targeting IL20RA to improve breast cancer treatment may be a potential novel strategy." (PMID 40097979, 2025). "For instance, there is notable upregulation of IL-20RA expression in pancreatic cancer (PC), breast cancer (BC), and non-small cell lung cancer (NSCLC), suggesting its potential role in cancer development and progression." (PMID 40806452, 2025). "Furthermore, IL20RA overexpression increased the lung metastasis of breast cancer in vivo." (PMID 33456560, 2021).
breast cancer (continued). "We also found that the expression level of IL20RA ligands IL-19, IL-20, and IL-24 was dramatically elevated in the serum of breast cancer patients compared to that of healthy donors, indicating that IL20RA signaling may play an important role in the progression of cancer." (PMID 33456560, 2021). "To determine whether IL20RA plays a role in breast carcinomas and to further investigate its function in stemness regulation, we examined the expression of IL20RA and SOX2 using tissue microarrays containing human normal/para-carcinoma breast tissues and breast tumors." (PMID 33456560, 2021). "Previous research has indicated that IL20RA can activate JAK1-STAT3 signaling pathways and is highly expressed in human breast cancer." (PMID 39765872, 2024). "The expression of IL20RA was positively correlated with that of SOX2 in tumors and noncancerous tissues of both breast cancer and colorectal cancer patients." (PMID 33456560, 2021).
psoriasis (9 papers, 2013 to 2024). An autoimmune condition characterized by red, well-delineated plaques with silvery scales that are usually on the extensor surfaces and scalp. "The ILR-encoding genes associated with psoriasis are IL20RA, IL28RA, and IL36RN." (PMID 37569685, 2023). "Polymorphisms in the IL20 receptor (IL20RA) have also been associated with psoriasis." (PMID 24069534, 2013). "IL-26 was expressed in psoriasis patients in combination with the IL-26 receptor, IL-10RB, and IL-20RA expressed by keratinocytes." (PMID 32290250, 2020). "To date, IL22RA1 had been only associated to inflammatory responses in airway epithelia by genetic studies, and IL20RA to psoriasis." (PMID 31693680, 2019). "IL20RA codes for a receptor for IL20, a cytokine that may be involved in epidermal function and is associated with psoriasis in the Caucasian population." (PMID 39857589, 2024). "Additionally, the primary focus of research on IL20RA lies within its role in regulating immune responses particularly related to autoimmune diseases such as psoriasis and rheumatoid arthritis." (PMID 39765872, 2024). "Interestingly, IL20RA was found to be upregulated in other immune-mediated diseases such as psoriasis and rheumatoid arthritis, pointing out these subunits as important for inflammatory diseases." (PMID 31426584, 2019).
colorectal cancer (6 papers, 2021 to 2025). A primary or metastatic malignant neoplasm that affects the colon or rectum. "JQ1 was demonstrated to decrease the transcriptionally activated eRNAs of SEs, causing the down-regulation of IL-20RA expression and inhibition of growth, metastasis and immune escape in colorectal cancer." (PMID 35514959, 2022). "JQ1 and iBET-151 can inhibit colorectal cancer development, metastasis, and IL-20RA expression, demonstrating that IL-20RA, activated by super enhancers, affects colorectal cancer cell proliferation and immune escape." (PMID 39838405, 2025). "Another gene of interest-IL20RA, has been involved in the development and progression of colorectal cancer (CRC)." (PMID 39323886, 2024). "IL-20RA knockdown notably suppressed the proliferation, migration and invasion of colorectal cancer cells." (PMID 34336707, 2021). "The CRC-specific SE-driven gene IL-20RA is highly expressed in colorectal cancer tissue, leading to poor clinical characteristics and prognosis." (PMID 34336707, 2021). "Correlation between IL-20RA expression and clinical characteristics in 118 colorectal cancer tissues." (PMID 34336707, 2021). "Additionally, some studies have suggested the presence of oncogenic SEs in colorectal cancer and confirmed their involvement in regulating oncogenic and immune pathways in colorectal cancer by modulating IL-20RA expression, affecting cell proliferation and immune evasion-related gene ecpression." (PMID 35514959, 2022). "IL-20RA knockdown could reduce cell proliferation, migration and invasion through several oncogenic and immune response pathways, suggesting that IL-20RA could be a potential target in the diagnosis and treatment of colorectal cancer." (PMID 34336707, 2021). "Higher expression of IL20RA and SOX2 was also found in colorectal cancer tissues compared with matched para-carcinoma or normal tissues." (PMID 33456560, 2021). "Thus, IL-20RA may serve as a novel potential target for colorectal cancer." (PMID 34336707, 2021).
autoimmune disease (5 papers, 2016 to 2024). A disorder resulting from loss of function or tissue destruction of an organ or multiple organs, arising from humoral or cellular immune responses of the individual to their own tissue constituents. "Recent studies have identified IL20RA is a novel risk gene for a variety of autoimmune diseases." (PMID 34852762, 2021). "In summary, this study demonstrates that SNPs carried on the ∼109 kb SLE risk haplotype facilitate hypermorphic IL20RA and IFNGR1 expression, while suppressing TNFAIP3 expression, adding to the mechanistic potency of this critically important locus in autoimmune disease pathology." (PMID 36199584, 2022).
bladder cancer (3 papers, 2012 to 2022). "Besides, IL20RA expression is also positively correlated with the clinical outcome of patients in patients of bladder carcinoma, uterine corpus endometrial carcinoma, rectum adenocarcinoma, and gastric cancer." (PMID 34114949, 2021).
colon carcinoma (3 papers, 2013 to 2021). "Analysis of GSE1323 revealed higher expression of IL20RA in the cell line derived from corresponding metastasis than in that derived from primary colon tumor." (PMID 33456560, 2021).
Arthritis (2 papers, 2018 to 2025). Inflammation of a joint. "The observed arthritis may potentially relate to PEX7 deletion, while deletions in IL20RA and IL22RA2 might exacerbate inflammatory dysregulation or skin eruption." (PMID 40859316, 2025).
Autoimmunity (2 papers, 2016 to 2024). The occurrence of an immune reaction against the organism's own cells or tissues. "While IL20RA has been extensively investigated for its role in immune modulation and autoimmunity, its association with oxidative stress remains relatively unexplored." (PMID 39765872, 2024). "Chromatin looping and eQTL experiments strongly support IL20RA as a putative causal autoimmunity gene in 6q23." (PMID 27799070, 2016). "It would be interesting to explore whether this autoimmunity associated variant exerts its pathogenic effect through a disruption of the TAD boundary between IL20RA and potential regulatory elements that would not otherwise interact with it." (PMID 27799070, 2016).
COVID-19 (2 papers, 2021 to 2022). A disease caused by infection with severe acute respiratory syndrome coronavirus 2. "This was observed for TGFB3, CCL4, IL15, and IL20RA in both ICM samples vs. COVID-19 samples and NIDCM samples vs. COVID-19 samples." (PMID 34071557, 2021). "Cytokine-related genes that are dysregulated in both cardiomyopathy patients and COVID-19 patients include chemokines (CCL3, CCL4, CXCL4, etc.), interleukins or interleukin receptors (IL15, IL20RA, etc.), and genes in the transforming growth factor beta (TGFB) family." (PMID 34071557, 2021).
lung carcinoma (2 papers, 2019 to 2022). "In addition, the expression of IL20RA, the gene encoding the α subunit of IL-20R, was neither obviously regulated in lung cancer nor correlated to patient survival." (PMID 36006737, 2022).
ovarian carcinoma (2 papers, 2021 to 2024). A malignant neoplasm originating from the surface ovarian epithelium. "Dramatically decreased IL20RA in human ovarian cancer (OC) peritoneal metastases and its correlation with the clinical outcome." (PMID 34114949, 2021). "IL20RA mediates a direct crosstalk between ovarian cancer (OC) cells and macrophages to regulate the polarization of macrophages." (PMID 34114949, 2021). "IL-18 is the essential factor downstream IL-20/IL20RA signaling to prevent the ovarian cancer dissemination." (PMID 34114949, 2021). "High-throughput CRISPR screen identified IL20RA as a suppressor of the transcoelomic metastasis of ovarian cancer (OC)." (PMID 34114949, 2021). "Characterization of IL20RA-mediated modulation on the peritoneal immune microenvironment during the transcoelomic metastasis of ovarian cancer (OC)." (PMID 34114949, 2021). "However, in patients with ovarian cancer, IL20RA is considered a crucial factor for preventing peritoneal metastasis of ovarian cancer cells by potentially creating an immunosuppressive microenvironment that inhibits metastasis." (PMID 39765872, 2024).
pancreatic tumor (2 papers, 2020). "In pancreatic tumor tissue as well as in pancreatic tumor cell lines, IL10RB and IL20RA were co-expressed and enable IL26 signaling." (PMID 31948053, 2020).
viral infection (2 papers, 2021 to 2025). "Future studies can design small molecules targeting IL-20RA and receptor signaling to test the potential of blocking IL-20RA to reduce viral infections." (PMID 41550952, 2025). "More importantly, IL-20RA cytokines aggravate viral infection with the elevated axis of T cell–IL-10–M2 macrophage to suppress the protective axis of M1 macrophage–IL-12–macrophage–IFN-γ in mice." (PMID 41550952, 2025). "The EV-A71 and HSV-1 results show that the important role of IL-20RA cytokines is found in neonatal mice with systemic viral infections, and further studies are needed to address this issue in future." (PMID 41550952, 2025). "Very few reports investigate the interaction of IL-20RA cytokines with viral infections." (PMID 41550952, 2025). "The interaction of IL-20RA cytokines with viral infection remains unknown, likely because these cytokines share receptors, functions, and activities." (PMID 41550952, 2025). "We found that IL-20RA cytokines induce macrophage polarization and aggravate viral infections." (PMID 41550952, 2025).
breast tumors (1 paper, 2021). "Elevated expressions of IL20RA and SOX2 in breast tumor tissues were detected when compared to the matched para-carcinoma tissues." (PMID 33456560, 2021). "Although overexpression of IL20RA in breast tumor cells decreased the percentage of CD8+ T-cells in the tumor microenvironment, NPs-Stattic-IL20RA plus IgG did not increase the percentage of these cells compared with the IgG control." (PMID 33456560, 2021).
cardiac hypertrophy (1 paper, 2025). "The IL-20RA-mediated signaling pathways contribute to cardiac hypertrophy by activating pro-inflammatory cytokines, which induce hypertrophic pathways in cardiomyocytes and the myocardial microenvironment." (PMID 40797392, 2025).
Colorectal Tumor (1 paper, 2021). "The expression of IL-20RA was significantly higher in colorectal tumor tissues than in corresponding normal tissues in all stages." (PMID 34336707, 2021).
depression (1 paper, 2024). "After adjusting for potential confounders, such as BMI and smoking, and correcting for multiple testing, four proteins remained significantly associated with depression: fibroblast growth factor 21 (FGF21), FGF19, Interleukin-6 (IL-6) and Interleukin-20 receptor subunit alpha (IL-20RA)." (PMID 39523673, 2024).
glaucoma (1 paper, 2016). Increased pressure in the eyeball due to obstruction of the outflow of aqueous humor. "In glaucoma patients with the IL-20RB mutation, the IL-20 family of cytokines would not bind efficiently to the IL-20RA/RB receptor so STAT3 would not be activated and translocated to the nucleus." (PMID 26903709, 2016). "IL-20, IL-24, IL-20RA, and IL-20 RB are expressed in the retina and optic nerve head in the DBA/2J mouse model of glaucoma (see later)." (PMID 26903709, 2016).
hypertrophic cardiomyopathy (1 paper, 2025). A condition in which the myocardium is hypertrophied without an obvious cause. "This Mendelian randomization study investigated the causal relationship between phosphatidylinositol (PI) levels and hypertrophic cardiomyopathy (HCM) risk, while evaluating the potential mediating role of interleukin-20 receptor subunit alpha (IL-20RA)." (PMID 40797392, 2025).
lymph node metastasis (1 paper, 2021). "High IL20RA expression was associated with greater tumor diameter, lymph node metastasis, and poor TNM stage in CRC, while also being suggestive of poor prognosis." (PMID 34820194, 2021). "In the analysis of clinical characteristics, we found that higher expression of IL20RA protein was associated with poor biological behavior, such as larger tumor size, lymph node metastasis, and poor TNM stage." (PMID 34820194, 2021). "CRC patients with lymph node metastasis had significantly higher IL20RA expression than those without it (P = 0.017)." (PMID 34820194, 2021).
melanoma (1 paper, 2013). A malignant, usually aggressive tumor composed of atypical, neoplastic melanocytes. "However, it should also be pointed out that additional new genes (IL20RA, HEPB2 and PERP) that are located in this region and are downregulated might make significant contributions to melanoma progression." (PMID 23383013, 2013).
metastasis (1 paper, 2021). The spread or migration of cancer cells from one part of the body (where they first appeared) to another.